INS (insulin)
Diseases named in the same sentence as INS in open-access papers (continued):
Sharing a sentence is not in itself a finding about the gene and the disease.
Insulin resistance (continued). "High brain insulin sensitivity is associated with weight loss and related to a favorable fat distribution, whereas insulin resistance is linked to visceral adiposity and pathological accumulation of intrahepatic fat content." (PMID 33800837, 2021). "Insulin resistance inside the liver, linked to the alterations in post-receptor insulin signaling, leads to increased gluconeogenesis, with further harmful impacts on glycemic homeostasis." (PMID 34201382, 2021). "Deficiency of insulin leads to increased gluconeogenesis, glycogenolysis and protein breakdown in skeletal muscle, and insulin resistance is characterized by increased proteolysis and decreased protein synthesis." (PMID 34830706, 2021). "The onset of type 2 diabetes (T2D) is due to a progressive loss of adequate β-cell insulin secretion, frequently under a background of insulin resistance." (PMID 33505497, 2021). "Body fatness is positively associated with increasing blood insulin levels, causing a diminished cellular response to insulin termed insulin resistance." (PMID 34822385, 2021). "These risk factors lead to insulin resistance, which initially prompts an increase in insulin production but causes decreased insulin secretion over time." (PMID 33413645, 2021). "Inadequate insulin signaling or impaired cellular response to insulin, termed as insulin resistance, is among the causes of mitochondrial dysfunction in the development and progression of PD." (PMID 33497031, 2021). "Insulin resistance (reduced insulin sensitivity) is associated with many conditions including a high-fat diet, lipid infusion, type 2 diabetes, obesity, and starvation." (PMID 34258288, 2021). "Our present data highlight a role for LCAC in the regulation of the molecular mechanisms of insulin signalling and explain the aspects of insulin resistance and hyperinsulinaemia, which are associated with type 2 diabetes." (PMID 34208786, 2021). "For example, inhibition of colonic macrophage recruitment in the gut promotes insulin sensitivity, and accumulation of macrophages in adipose tissue is associated with insulin resistance." (PMID 34886800, 2021). "Factor analysis revealed that BMI/insulin/lipids, BMI/insulin/glucose, and blood pressure—with a unifying role for markers of insulin resistance and adiposity—underlie the MS among the Canadian youth." (PMID 33671739, 2021). "Its variants also showed association with decreased fasting plasma insulin and homeostatic model assessment of insulin resistance, indicating a plausible effect through impaired insulin secretion." (PMID 34017037, 2021). "This condition was associated with elevated circulating glucose and insulin levels, suggesting the presence of insulin resistance." (PMID 33888702, 2021). "Given sex differences in insulin levels and susceptibility to develop insulin resistance, we further considered boys and girls separately." (PMID 34243726, 2021). "A deficiency of insulin synthesis in pancreatic cells causes type 1 diabetes (T1D), whereas type 2 diabetes (T2D) is caused by insulin resistance, which causes the body to utilize insulin inefficiently." (PMID 34925466, 2021). "It is also possible that greater H2O2 production is associated with greater insulin sensitivity as a recent study in rodents found insulin resistance to be associated with lower H2O2 production." (PMID 34605220, 2021). "First, we did not have glucose measurements in early pregnancy or 30 min or 1 h glucose and insulin measurements at OGTT to further explore the associations of B12/folate with beta cell function or insulin resistance." (PMID 34296321, 2021). "T1DM is characterized by autoimmune destruction of pancreatic β-cells resulting in severe insulin deficiency, and T2DM results from a combination of insulin resistance and dysfunction of insulin-producing pancreatic β-cells." (PMID 34135959, 2021).
Insulin resistance (continued). "This is associated with insulin resistance, in the early pregnancy, insulin sensitivity increases, which promotes the growth of adipose and energy storage." (PMID 33930086, 2021). "Reduced insulin clearance by liver would cause hyperinsulinemia, resulting in peripheral insulin resistance by overexposure to endogenous insulin." (PMID 33668109, 2021). "Remarkably, the liver-specific deficiency of Sphk2 exhibits pronounced insulin resistance and glucose intolerance, demonstrating a key role of hepatic SphK2 in the regulation of insulin sensitivity and glucose homeostasis." (PMID 34530846, 2021). "GDM is associated with increased maternal insulin resistance of pregnancy that cannot be met by a sufficient pancreatic insulin response to lower blood glucose to normal levels." (PMID 33450885, 2021). "Insulin resistance has also been linked to hypertension because insulin can cross the blood-brain barrier (BBB) to the central nervous system (CNS) and activate the systemic nervous system (SNS)." (PMID 33557218, 2021). "mTOR-S6K1-mediated phosphorylation of IRS-1, and degradation of IRS-1 and InsR via the proteasomal or lysosomal pathway, respectively, were implicated in the mechanism of insulin-induced insulin resistance in these NPY/AgRP-expressing cells." (PMID 34831343, 2021). "This adipokine is involved in the regulation of insulin sensitivity and is known to be associated with obesity and insulin resistance in T2DM interfering with insulin function, affecting glycogen metabolism and decreasing glucose uptake in skeletal muscle." (PMID 34652617, 2021). "Adding to the depth of the IL-6 cascade signaling chain of events, elevations in IL-6 from contracting muscles have been noted to increase insulin sensitivity and possibly decrease ones risk of developing insulin resistance, the precursor for T2DM." (PMID 34179543, 2021). "On the other hand, the inability and dysfunctional adipose tissue cause decreased secretion of insulin-sensitizing adipokines, such as leptin and adiponectin, contributing to insulin resistance." (PMID 34407873, 2021). "The aim of this review is to summarize the impact of the transmembrane receptor-like PTPs (RPTPs) in the insulin signaling cascade and secretion, and their putative implication in metabolic diseases associated to insulin resistance such as obesity and T2DM." (PMID 34071721, 2021). "PPAR-γ is known to be a major regulator of adiponectin gene transcription and an important biological indicator associated with the insulin signaling pathway, insulin resistance, and inflammation." (PMID 34257685, 2021). "Between the TLR ligands, High Mobility Group Box1 (HMGB1) has peculiar properties since modulating insulin resistance and insulin secretion, and it was positively associated with increased body mass index, insulin resistance, and hyperglycemia." (PMID 34360753, 2021). "In conclusions, insulin treatment in type 2 diabetes was closely associated with increased risk of carotid atherosclerotic lesions, which partly attributed to severe insulin resistance in patients receiving insulin therapy." (PMID 33598483, 2021). "Type 2 diabetes (T2D) is thought to be a complication of metabolic syndrome caused by disorders of energy utilization and storage and characterized by insulin resistance or deficiency of insulin secretion." (PMID 34368359, 2021). "The increased HOMA-IR in old untreated rats was associated with insulin resistance in insulin-dependent tissues such as skeletal muscle and visceral adipose tissue where insulin failed to activate the PI3K/Akt pathway as it did in young rats." (PMID 34356299, 2021). "Mg deficiency was also found to be associated with insulin resistance in obesity due to modulation of insulin receptor phosphorylation as well as insulin secretion." (PMID 34064348, 2021). "These amino acids have been reported to be associated with insulin resistance and impaired insulin secretion, key factors of cancer and obesity pathogenesis." (PMID 33926456, 2021).
Insulin resistance (continued). "Peripheral insulin resistance is hallmarked by hyperglycemia associated with compensatory hyperinsulinemia (by augmented pancreatic insulin production)." (PMID 34575946, 2021). "It has been reported that oxidative stress was one of the causes of insulin resistance and impaired insulin secretion, which eventually leads to T2DM." (PMID 34771066, 2021). "Insulin resistance developing in GK rats is strongly associated with abnormal insulin signaling in the metabolically active tissues." (PMID 33671110, 2021). "It is characterized by chronic hyperglycemia, insulin resistance, and/or insulin secondary deficiency caused by the failure of β-pancreatic cells." (PMID 34182970, 2021). "First, P2Y2R deficiency effectively improved insulin resistance with a reduction in body weight and plasma insulin." (PMID 34073834, 2021). "We aim to assess the association of empirical dietary (EDIH) and lifestyle (ELIH) index for hyperinsulinemia with the risk of insulin resistance, hyperinsulinemia, insulin sensitivity, and β-cell dysfunction in Iranian adults." (PMID 33985566, 2021). "ATP surplus in the pancreatic β-cells and α-cells causes excess secretion of insulin and glucagon, respectively, leading to peripheral insulin resistance in the early phase of type 2 diabetes." (PMID 34987473, 2021). "High-affinity insulin autoantibodies have been proposed to be involved in a mechanism underlying severe insulin resistance after insulin administration and have also been also studied as a marker of type 1 diabetes." (PMID 33953692, 2021). "Obesity causes insulin resistance by the pathogenesis where excess free fatty acids deposit in the liver, adipocytes, skeletal muscles, and the pancreas, triggering impairment in insulin signaling." (PMID 34070381, 2021). "Subjects with the major allele had higher insulin sensitivity, lower insulin resistance and lower plasma insulin level compared with subjects who were carriers of the minor allele." (PMID 34068889, 2021). "Proinflammatory cytokines can cause insulin resistance by inhibiting the insulin-signaling pathway and reducing the content of Glut4." (PMID 34884763, 2021). "Insufficient vitamin D is associated with a greater risk of infection, autoimmunity, cancer, insulin secretion and insulin resistance, metabolic bone disease, and osteoporosis." (PMID 34322512, 2021). "In the graphs showing the correlation of BMI and insulin secretion ability or insulin resistance, TYK2PV was plotted to visualize the association with these parameters." (PMID 33799705, 2021). "This is a secondary analysis of the WISER Survivor clinical trial examining the relative effect of exercise, weight loss and combined exercise and weight loss interventions on insulin and insulin resistance." (PMID 34578984, 2021). "We also address cognitive impairment and Alzheimer's disease, which are associated with insulin resistance, and the potential for combatting them with intranasal insulin and insulin sensitizers." (PMID 33845179, 2021). "T2D is characterized by relatively deficient insulin secretion from pancreatic islet β-cells combined with insulin resistance in target organs." (PMID 34658856, 2021). "Particularly, impaired hippocampal insulin signaling is associated with impairments in memory and other executive functions, and it is proposed as a mediator between peripheral insulin resistance in T2D and brain dysfunction in AD." (PMID 33967682, 2021). "Its dysregulation caused insulin hypothalamic resistance and deteriorated fatty acid metabolism with acute hepatic insulin resistance, describing hypothalamic Hsp10 as a potential mediator of the brain–liver axis." (PMID 33946318, 2021). "In large-scale cohorts, BCAAs have been inversely associated with insulin sensitivity and directly associated with insulin resistance, fasting blood glucose levels, and TG concentrations." (PMID 34677409, 2021).
Insulin resistance (continued). "This review examines the crosstalk between autophagy and insulin action, with specific focus on dysregulated autophagy as a cause or consequence of insulin resistance." (PMID 34336862, 2021). "These alterations are all associated with insulin resistance, either resulting from impaired insulin action, or as a result of the exaggerated levels of the hormone, which has negative consequences as well." (PMID 33919569, 2021). "Most obese individuals have elevated plasma levels of free fatty acids (FFA), which cause peripheral (muscle) insulin resistance by inhibiting insulin-stimulated glucose uptake and glycogen synthesis." (PMID 33668426, 2021). "Insulin resistance in obesity and type 2 diabetes is caused by decreased insulin-stimulated glucose transport and metabolism in adipocytes." (PMID 34086709, 2021). "In a joint model, only insulin resistance and reduced insulin secretion were associated with dysglycemia." (PMID 34206745, 2021). "Generally, the main cause of hyperinsulinemia is insulin resistance, which the pancreas compensates for by producing more insulin." (PMID 34203830, 2021). "Insulin resistance in the muscles is caused by the decreased recruitment of the glucose transporter 4 (GLUT-4) proteins to the plasma membrane in response to insulin." (PMID 34712528, 2021). "BCAAs play an essential role in physiologically switching off the insulin signaling; however, when present in excess, they are associated with insulin resistance and T2DM development." (PMID 34680047, 2021). "Studies have reported that short-term treatment with IL-6 improves insulin-induced glucose uptake in skeletal muscles, although sustained treatment with IL-6 causes glucose intolerance and insulin resistance." (PMID 34943061, 2021). "Both TNF-α and IL-6 have been associated with obesity and insulin resistance and can alter insulin sensitivity by prompting different phases in the insulin signaling pathway, stimulating hepatic lipogenesis, and impairing insulin signaling." (PMID 34221262, 2021). "Adiponectin is known to increase insulin sensitivity, with low adiponectin plasma concentrations associated with insulin resistance." (PMID 33799409, 2021). "Increased insulin, a marker for insulin resistance, has been implicated in gut permeability, and impaired fasting glucose subjects show higher markers of gut permeability than controls." (PMID 34381434, 2021). "Adiponectin has insulin-sensitising, anti-atherogenic and anti-inflammatory properties, and hypoadiponectinemia has been associated with insulin resistance and T2DM." (PMID 33467592, 2021). "Palmitate, a saturated fatty acid, has been shown to decrease insulin-stimulated glucose uptake and reduce the insulin-stimulated phosphorylation of Akt, suggesting that palmitate causes insulin resistance in C2C12 muscle cells." (PMID 33799458, 2021). "At present, the pathogenesis of type 2 diabetes is mainly divided into two aspects: One is the deficiency of insulin secretion, and the other is the insulin resistance." (PMID 34026064, 2021). "Increases in saturated long-chain fatty acids, diverse sphingolipids, or ceramides are linked to insulin resistance, indicating that an increase in overall fatty acid and lipid metabolism is detrimental for insulin action." (PMID 33946318, 2021). "Typical symptoms of T2DM associated with insulin dysfunction, including hyperglycemia, insulin resistance, and relative insulin deficiency, also induce the accumulation of Aβ in the brain, contributing to AD pathogenesis." (PMID 34489627, 2021). "Sphingolipids have previously been shown to be associated with insulin resistance, possibly via downstream insulin signaling alterations." (PMID 34426590, 2021). "The presence of both obesity and periodontal disease significantly increases the risk for diabetes because of the exacerbated insulin resistance due to periodontitis, which further increases glucose and insulin levels in blood." (PMID 34463983, 2021).
Insulin resistance (continued). "Insulin resistance (IR), characterized by an inadequate physiological response with insensitivity to insulin, is a major risk factor for metabolic syndrome and cardiovascular diseases (CVD)." (PMID 33800541, 2021). "We also tested if the changes in (FM/LM) between genotypes and diets were associated with increased fasting blood glucose and serum insulin levels as hallmarks of insulin resistance." (PMID 34204316, 2021). "T2DM is characterized by the presence of chronic fluctuating hyperglycemia, obesity-associated insulin resistance as well as the impaired secretion of insulin and dysfunction of the incretin system." (PMID 34131405, 2021). "Insulin is a growth factor, and hyperinsulinemia present in insulin resistance is associated with lower levels of sex hormone binding globulin, thereby increasing the availability of unbound free androgens." (PMID 33562646, 2021). "The clinical consequences of hypomagnesemia include impaired insulin secretion, insulin resistance, and increased macrovascular risk." (PMID 33567588, 2021). "Obesity-associated breast cancer recurrence is mechanistically linked with elevated insulin levels and insulin resistance." (PMID 34578984, 2021). "Insulin resistance and/or hypersecretion of insulin caused by obesity are thought to be important causes of T2DM." (PMID 33668426, 2021). "In our study, however, the female offspring displayed insulin resistance associated with increased insulin secretion but normal beta-cell mass." (PMID 35111136, 2021). "Second, we performed insulin tolerance tests to determine the effect of P2Y2R deficiency on insulin resistance." (PMID 34073834, 2021). "Severity of stress was positively associated with insulin secretion, an early feature of insulin resistance suggesting that prenatal stress is an independent predictor of metabolic outcomes in adolescence." (PMID 33481865, 2021). "When immune cells are activated for immune responses, the release of cytokines can weaken the insulin signal and cause insulin resistance over time." (PMID 35127566, 2021). "Monogenic causes of insulin resistance are usually severe and associated with rare inherited disorders resulting from mutations in the insulin signaling pathway." (PMID 33995269, 2021). "Hyperleptinemia is a feature of other metabolic conditions and is associated with systemic insulin resistance, where insulin is a known leptin secretagogue." (PMID 33848268, 2021). "The main pathogenic mechanism of GDM is an increase in maternal insulin resistance due to increased secretion of insulin-resistance hormones from the placenta, necessitating increased pancreatic β-cell insulin secretion." (PMID 33776619, 2021). "A combination of insulin resistance and decreased insulin secretion is expected to increase the risk for T2DM." (PMID 34630157, 2021). "It has been reported that GDM women have a decreased ability to compensate for oxidative stress, and this was associated with increased insulin resistance and reduced insulin secretion." (PMID 34360849, 2021). "Insulin resistance is a feature that is very usually linked with obese people and it results in high level of circulating insulin, a well-established risk factor for cancer and which is also accompanied by marked changes in the levels of inflammatory markers." (PMID 34535145, 2021). "Insulin resistance, which occurs when insulin levels are sufficiently high over a prolonged period, causing the cells to fail to respond normally to the hormone." (PMID 34358068, 2021). "We also found that follistatin associated with adipose tissue insulin resistance and related traits, and that follistatin attenuated insulin-mediated suppression of lipolysis in adipocytes." (PMID 34759311, 2021). "A loss of neuronal sensitivity to insulin, referred to as insulin resistance, coincides with their dysfunction and disease." (PMID 33799628, 2021).